SLC39A4 (solute carrier family 39 member 4)
Description:
Selective transporter that mediates the uptake of Zn(2+). Plays an essential role for dietary zinc uptake from small intestine (By similarity). The Zn(2+) uniporter activity is regulated by zinc availability. Also exhibits polyspecific binding and transport of Cu(2+), Cd(2+) and possibly Ni(2+) but at higher concentrations.
Synonyms: ZIP-4; ZIP4; AWMS2; AEZ
Tractability: Antibody: UniProt places it where antibodies can reach, with high confidence; its Gene Ontology location is reachable by antibodies, with high confidence; UniProt predicts a signal peptide or a membrane-spanning region. PROTAC: UniProt records ubiquitination sites on it.
Gene: Protein-coding gene on chromosome 8 (144,409,742 to 144,416,844, reverse strand). Ensembl gene ENSG00000147804.
Subcellular location: Cell membrane; Recycling endosome membrane; Apical cell membrane
Pathways (Reactome):
Disease: Defective SLC39A4 causes acrodermatitis enteropathica, zinc-deficiency type (AEZ)
Transport of small molecules: Zinc influx into cells by the SLC39 gene family
Gene Ontology:
Molecular function: identical protein binding; metal ion binding; zinc ion binding; zinc ion sensor activity; zinc ion sequestering activity; zinc ion transmembrane transporter activity; monoatomic cation:bicarbonate symporter activity; metal ion transmembrane transporter activity
Biological process: zinc ion transmembrane transport; intracellular monoatomic cation homeostasis; intracellular zinc ion homeostasis; zinc ion import across plasma membrane; bicarbonate transport; metal ion transport; transmembrane transport
Cellular component: cytoplasmic vesicle; plasma membrane; recycling endosome membrane; apical plasma membrane; membrane
Genetic constraint (gnomAD): Loss-of-function variants: 51 observed, 51.05 expected, observed/expected ratio (o/e) 1, 90% interval 0.8 to 1.26. The synonymous counts are far from expectation, so gnomAD's model fits this gene poorly and the ratio says little. Missense variants: 993 observed, 809.16 expected, observed/expected ratio (o/e) 1.23, 90% interval 1.16 to 1.29. Synonymous variants: 540 observed, 396.85 expected, observed/expected ratio (o/e) 1.36, 90% interval 1.27 to 1.46.
Gene-disease validity (ClinGen):
ClinGen rates the evidence that SLC39A4 causes each of these diseases.
acrodermatitis enteropathica (autosomal recessive): Definitive. Acrodermatitis enteropathica (AE) is a rare inherited inborn error of metabolism resulting in a severe zinc deficiency and characterized by acral dermatitis, alopecia, diarrhea and growth failure.
Homologues: Orthologues: chimpanzee SLC39A4 (98% identical), macaque SLC39A4 (95% identical), dog SLC39A4 (78% identical), pig SLC39A4 (77% identical), guinea pig SLC39A4 (75% identical), rat Slc39a4 (72% identical), mouse Slc39a4 (72% identical), tropical clawed frog slc39a4 (42% identical), Drosophila melanogaster foi (22% identical), zebrafish slc39a4 (15% identical), Caenorhabditis elegans zipt-15 (15% identical). Paralogues in human: SLC39A12 (32% identical), SLC39A6 (23% identical), SLC39A10 (23% identical), SLC39A5 (23% identical), SLC39A14 (21% identical), SLC39A8 (21% identical).
Diseases named in the same sentence as SLC39A4 in open-access papers:
SLC39A4 is named in the same sentence as 53 diseases in open-access papers, as found by Europe PMC text mining. Sharing a sentence is not in itself a finding about the gene and the disease. The quoted sentences say what the papers report.
acrodermatitis enteropathica (28 papers, 2011 to 2025). "Inherited zinc deficiency condition acrodermatitis enteropathica, which occurs due to mutation in the SLC39A4 gene (encoding ZIP4), presents from birth." (PMID 38367035, 2024). "Mutations in SLC39A4 gene-encoding ZIP4 were shown to be related to acrodermatitis enteropathica and its expression is decreased." (PMID 35736421, 2022). "Workup for acrodermatitis enteropathica includes measuring plasma zinc concentration levels and screening for the SLC39A4 gene mutation." (PMID 34787024, 2021). "We further illustrate how this functional mechanism is affected by genetic variants in SLC39A4 that in turn lead to Acrodermatitis enteropathica, a rare condition of Zn2+ deficiency." (PMID 31979155, 2020). "Acrodermatitis enteropathica (AE) is a rare autosomal recessive hereditary skin disease caused by mutations in the SLC39A4 gene and is characterized by periorificial dermatitis, alopecia and diarrhoea due to insufficient zinc absorption." (PMID 31987033, 2020). "This is one difference between SLC39A8 and, say, SLC39A4—mutations in which are well-known to cause acrodermatitis enteropathica, zinc-deficiency (AEZ) type." (PMID 31521203, 2019). "Acrodermatitis enteropathica (OMIM 201100) is an autosomal recessive disorder caused by biallelic sequence variants in the SLC39A4 gene (OMIM 607059) located on chromosome 8q24." (PMID 31835360, 2019). "We have previously identified a SLC39A4 promoter variant (c.−169A>G) that causes acrodermatitis enteropathica (AE) via disruption of a conserved CCAAT box29." (PMID 40501650, 2025). "Its clinical manefestations are similar to Acrodermatitis enteropathica (AE), which is a genetic zinc absorption disorder caused by SLC39A4 gene mutations." (PMID 38755601, 2024). "Severe zinc deficiency was found to be related to Acrodermatitis enteropathica (AE), a potentially fatal genetic disorder in which individuals are unable to absorb sufficient dietary zinc as a result of mutations in the SLC39A4 gene which encodes hZIP4." (PMID 29295546, 2017). "The ZIP transporter proteins appear to serve crucial roles in metal homeostasis and perhaps unappreciated important signaling pathways; for example, mutations in the human SLC39A4 gene are responsible for acrodermatitis enteropathica, zinc-deficiency (AEZ)." (PMID 22563477, 2012). "And mutations in SLC39A4, the gene that encodes ZIP4, result in the zinc deficiency disorder acrodermatitis enteropathica." (PMID 41583444, 2025). "Inherited zinc deficiency is mostly associated with mutations in the SLC39A4 gene (which encodes for ZIP4), resulting in a triad of alopecia, diarrhoea and dermatitis in a condition known as acrodermatitis enteropathica." (PMID 38367035, 2024). "Thus, mutations in SLC39A4 give rise to Acrodermatitis enteropathica (AE), a rare autosomal, recessively inherited disorder of intestinal Zn malabsorption that is also called “genetic Zn deficiency”." (PMID 35745255, 2022). "Zinc deficiency in breast-fed full-term infants is sometimes caused by congenital acrodermatitis enteropathica (OMIM201100), which is caused by a mutation in the SLC39A4/ZIP4 gene, and results in reduced intestinal zinc absorption." (PMID 23741301, 2013). "Conditional knockout of the intestinal zinc transporter Zip4 (Slc39a4) in mice creates a model of the lethal human genetic disease acrodermatitis enteropathica (AE)." (PMID 24015258, 2013). "Patients with Acrodermatitis Enteropathica (AE), who suffer from severe skin disease and frequent infections, have unusually low serum concentrations of Zn due to pathogenic loss-of-function mutations in SLC39A4." (PMID 21445361, 2011). "Acrodermatitis enteropathica (AE, OMIM 201100) is a rare autosomal recessive dermatosis characterized by periorificial dermatitis, diarrhea, alopecia, and hypozincaemia due to pathogenic variants of SLC39A4." (PMID 38831989, 2024).
acrodermatitis enteropathica (continued). "Similarly, mutations in SLC39A4 (ZIP4) and SLC39A13 (ZIP13) have been linked to Zn deficiency and/or accumulation in specific cellular compartments resulting in acrodermatitis enteropathica and spondylocheiro dysplastic Ehlers-Danlos syndrome, respectively." (PMID 29621230, 2018). "As leading examples, mutations in ZIP4 (SLC39A4) and ZIP13 (SLC39A13) are responsible for the rare lethal autosomal-recessive inherited zinc deficiency disease, acrodermatitis enteropathica (AE), and Ehlers-Danlos Syndrome (EDS), respectively." (PMID 30417019, 2018). "One is due to mutation in the SLC39A4 gene, which codes for zinc transporter ZIP4 in the affected individual and leads to impairment in the absorption of zinc from the gastrointestinal tract and hence low serum levels of the Zn (<50 mcg/dL); this is referred to as acrodermatitis enteropathica (AE)." (PMID 39051233, 2024).
Zinc deficiency (12 papers, 2013 to 2025). A deficiency of the essential metal Zinc; an essential cofactor for many enzymes. "Patients with AE experience severe zinc deficiency from birth because of mutations in SLC39A4 (ZIP4), which encodes a major intestinal zinc uptake protein." (PMID 40081495, 2025). "Affected members of our family carry a rare genetic variant, p.Gly512Trp in the SLC39A4 gene which encodes a zinc transporter; disease is thought to result from zinc deficiency." (PMID 30174688, 2018). "Symptomatic zinc deficiency can also appear from a combination of the SLC39A4 mutation in the infant and low milk zinc concentration from the mother who has the same heterozygous mutation." (PMID 25548552, 2014). "Moreover, a nonsense mutation in PLD4 and a splice variant in SLC39A4 are responsible for bovine hereditary zinc deficiency in Fleckvieh and Holstein cattle, respectively." (PMID 40240941, 2025). "Loss of function of SLC39A4 leads to a severe zinc deficiency, which ends fatally if untreated." (PMID 34573291, 2021). "We could not rule out whether mother and child presented heterozygosity for a SLC39A4 or SLC30A2 gene mutation or whether the clinical features could be due to a dietary zinc deficiency of the mothers and/or increased zinc requirements of the infants." (PMID 25548552, 2014). "In this model the loss-of-function of the zinc transporter ZIP4 (Slc39a4) specifically in the intestine rapidly causes zinc deficiency which is accompanied by a disruption of the integrity of the intestine and repression of the division of intestine stem cells and differentiation of their progeny." (PMID 24015258, 2013). "Remarkably, the correlation analysis between genotype frequencies at ZTGs and zinc deficiency in soil in South Asia did not result in any significant hit for SLC39A4, the main transporter at the apical membrane of enterocytes responsible for the absorption of dietary zinc." (PMID 35279701, 2022). "However, the PLD4 variant and the previously reported SLC39A4-associated zinc deficiency in Holstein cattle (BHZD) could be ruled out due to their clinical differences." (PMID 32448141, 2020).
alopecia (5 papers, 2020 to 2025). Hair loss usually from the scalp. "On the other hand, the genetic form is an autosomal recessive disorder, characterized by periorificial dermatitis, alopecia, and diarrhea caused by a defect in the SLC39A4 gene located on human chromosome 8, band 8q24.3, which impairs zinc absorption in the small intestine." (PMID 41625893, 2025).
pancreatic cancer (5 papers, 2021 to 2025). "Simultaneously, SLC39A4 manifests a notable upregulation in both pancreatic cancer cells and associated tissues." (PMID 38230214, 2024). "In pancreatic cancer cells, lipid synthesis potentiates expression of macropinocytosis-associated genes, including SDC1, DNM2, via the ZIP4 (solute carrier family 39 member 4) pathway." (PMID 40408281, 2025). "SLC39A4 shows significant upregulation in pancreatic cancer when compared to normal pancreatic tissues and has been proposed as a novel diagnostic marker for detecting the disease." (PMID 38230214, 2024). "Then, in 2009, the authors further deciphered the function of SLC39A4 by silencing it in a mouse pancreatic cancer model and found that cell proliferation, migration, and invasion were all suppressed and that survival outcomes were significantly improved." (PMID 33783998, 2021). "explained a potential mechanism in their study: SLC39A4 mediates pancreatic cancer cell growth by upregulating the expression of neuropilin‐1 (NRP‐1), vascular endothelial growth factor (VEGF), and matrix metalloproteases (MMPs) in cell lines and xenografts." (PMID 33783998, 2021). "Recent studies have suggested that low SLC39A1, SLC39A2 and SLC39A3 expression in prostate cancer, low SLC39A3 and high SLC39A4 expression in pancreatic cancer." (PMID 34615436, 2021). "Additionally, the expression levels of SLC39A4 in paracancerous and tumorous tissues derived from pancreatic cancer patients were meticulously authenticated." (PMID 38230214, 2024). "substantiated the role of SLC39A4 in pancreatic cancer progression." (PMID 33783998, 2021). "In addition to its function in cell proliferation, SLC39A4 is reported to upregulate the expression of VEGFs in pancreatic cancer by upregulating its receptor NRP‐1, revealing an autocrine signaling pathway involving the ZIP4–VEGF–NRP‐1 axis." (PMID 33783998, 2021). "Under gemcitabine treatment, a chemoresistant clone expressing EMT properties could be selected by inhibiting expression of the gemcitabine transporter ENT1 in pancreatic cancer cells via solute carrier family 39 member 4 (SLC39A4, also called ZIP4)-ZEB1 pathway." (PMID 37173915, 2023). "However, the detailed mechanism by which SLC39A4 regulates pancreatic cancer growth is not completely clear." (PMID 33783998, 2021).
lung carcinoma (4 papers, 2017 to 2024). "High expressed SLC39A4 is found in several malignances and associated with poorer prognosis, including lung cancer." (PMID 33535184, 2021). "Because tumour metastasis is significantly detrimental to the survival of patients with lung cancer, we further investigated the effects of SLC39A4 expression on lung cancer cell migration." (PMID 28775359, 2017). "SLC39A4 expression was significantly correlated with the expression of the lung cancer stem cell biomarkers CD44 and CD13323 (Z = 7.11, P < 0.00001)." (PMID 28775359, 2017). "Cell-based assays also demonstrated an important role for SLC39A4 in the diminished migratory potential, stemness, and chemoresistance of A549 lung cancer cells both in vitro and in vivo." (PMID 28775359, 2017). "In this study, a meta-analysis of data extracted from the GEO and TCGA databases revealed the clinical significance of SLC39A4 in lung cancer." (PMID 28775359, 2017). "SLC39A4 silencing by lentivirus-mediated shRNA blocked human lung cancer cell epithelial-mesenchymal transition and metastasis in vitro and in vivo, respectively." (PMID 28775359, 2017). "Collectively, these data suggest that SLC39A4 may play an important role in lung cancer pathophysiology." (PMID 28775359, 2017). "Moreover, SLC39A4 knockdown enhanced cancer cell sensitivity to cisplatin-induced death by inhibiting stemness in lung cancer cells." (PMID 28775359, 2017). "To study the role and function of SLC39A4 in NSCLC pathogenesis, we first assessed the levels of SLC39A4 expression in normal and lung carcinoma tissues in a meta-analysis of eight GEO datasets containing clinicopathological information." (PMID 28775359, 2017). "The zinc transporter SLC39A4 influences epithelial cell morphology and migration in various cancers; however, its role in regulating cell invasion and chemotherapeutic resistance in human lung cancer is not yet clear." (PMID 28775359, 2017).
breast carcinoma (3 papers, 2016 to 2021). "ZIP4 (gene name SLC39A4, a zinc transporter) plays tumor promoting roles in many cancer types, including pancreatic cancer, hepatocellular carcinoma, breast cancer, and glioma." (PMID 34359722, 2021). "Moreover, according to the cBioPortal for Cancer Genomics, 20% of breast cancer patients have an amplification in the Zip4 coding gene, Slc39a4." (PMID 34502091, 2021). "These subtype-specific breast cancer metabolism signatures contained a common set of five genes (SQLE, PYCRL, TSTA3, CYC1 and SLC39A4) which were co-amplified with MYC on chromosome 8q24 and showed a positive correlation with hypoxia." (PMID 27358048, 2016).
Cirrhosis (2 papers, 2022 to 2023). A chronic disorder of the liver in which liver tissue becomes scarred and is partially replaced by regenerative nodules and fibrotic tissue resulting in loss of liver function. "Compared to non-NAFLD of HCC patients with cirrhosis, GNG4, EPCAM, SPARCL1, DGKK, and SLC39A4 were down-regulated and HOXD9 was up-regulated in NAFLD of HCC patients with cirrhosis." (PMID 36397165, 2022).
melanoma (2 papers, 2010 to 2016). A malignant, usually aggressive tumor composed of atypical, neoplastic melanocytes. "In the Geo database, ample data on SLC39A4 suggested that elevated ZIP4 mRNA was found in lymphoma, melanoma, and metastatic colon cancer." (PMID 27611948, 2016).
non-small cell lung carcinoma (2 papers, 2017 to 2021). A group of at least three distinct histological types of lung cancer, including non-small cell squamous cell carcinoma, adenocarcinoma, and large cell carcinoma. "SLC39A4 can be used as a prognostic marker for gastric cancer and non-small cell lung cancer." (PMID 34630418, 2021). "Collectively, these data suggest that SLC39A4 may be a novel therapeutic target and predictive marker of tumour metastasis in non-small cell lung cancer." (PMID 28775359, 2017). "Here, integrated analysis of gene expression in non-small cell lung cancer revealed that SLC39A4 expression is significantly correlated with increased tumour size and regional lymph node spread, as well as shorter overall survival (OS) and disease-free survival (DFS)." (PMID 28775359, 2017).
acute myeloid leukemia (1 paper, 2024). Acute myeloid leukemia (AML) is a group of neoplasms arising from precursor cells committed to the myeloid cell-line differentiation. "However, downregulation of SLC39A4 was observed in kidney renal clear cell carcinoma (KIRC), acute myeloid leukemia (LAML), and LGG." (PMID 38230214, 2024).
gallbladder cancer (1 paper, 2024). "Interestingly, SLC39A4 expression is constitutionally downregulated in nude mice, reducing the growth and migration of gallbladder cancer cells and delaying the development of transplanted tumors." (PMID 38431620, 2024).
lymph node metastasis (1 paper, 2020). "For patients have no lymph node metastasis, high mRNA expression of SLC39A4 and SLC39A12 was also found to be correlated with worse OS." (PMID 32744318, 2020).
uveal melanoma (1 paper, 2025). A melanoma derived from melanocytes of the uveal tract. "In the uveal melanoma cohort, a six‐molecule signature (ARPC1B, BTBD6, GUSB, KRTCAP2, RHBDD3, and SLC39A4), which was associated with glycolysis and the immune response, was established and used for survival prediction and risk stratification of these patients." (PMID 39830021, 2025).